NEURL1B (neuralized E3 ubiquitin protein ligase 1B)
Description:
E3 ubiquitin-protein ligase involved in regulation of the Notch pathway through influencing the stability and activity of several Notch ligands.
Synonyms: NEUR2; DKFZP761M1511; RNF67B; hNeur2
Tractability: PROTAC: ubiquitination databases record sites on it.
Gene: Protein-coding gene on chromosome 5 (172,641,248 to 172,691,540, forward strand). Ensembl gene ENSG00000214357.
Subcellular location: Cytoplasm
Subcellular location (Human Protein Atlas): Cytosol; Actin filaments
Pathways (Reactome):
Disease: Constitutive Signaling by NOTCH1 HD Domain Mutants; Constitutive Signaling by NOTCH1 HD+PEST Domain Mutants; Constitutive Signaling by NOTCH1 PEST Domain Mutants
Signal Transduction: Activated NOTCH1 Transmits Signal to the Nucleus; NOTCH2 Activation and Transmission of Signal to the Nucleus; NOTCH3 Activation and Transmission of Signal to the Nucleus
Gene Ontology:
Molecular function: protein binding; ubiquitin protein ligase activity
Biological process: ubiquitin-dependent endocytosis; protein ubiquitination
Cellular component: cytosol; early endosome; cytoplasm
Genetic constraint (gnomAD): Loss-of-function variants: 13 observed, 19.72 expected, observed/expected ratio (o/e) 0.66, 90% interval 0.43 to 1.05. The synonymous counts are far from expectation, so gnomAD's model fits this gene poorly and the ratio says little. Missense variants: 790 observed, 563.04 expected, observed/expected ratio (o/e) 1.4, 90% interval 1.32 to 1.49. Synonymous variants: 432 observed, 280.49 expected, observed/expected ratio (o/e) 1.54, 90% interval 1.42 to 1.67.
Homologues: Orthologues: macaque NEURL1B (99% identical), chimpanzee NEURL1B (99% identical), dog NEURL1B (98% identical), pig NEURL1B (97% identical), mouse Neurl1b (91% identical), rat Neurl1b (91% identical), tropical clawed frog neurl1b (65% identical), zebrafish neurl1b (64% identical), guinea pig NEURL1B (55% identical), rabbit NEURL1B (55% identical). Paralogues in human: NEURL1 (42% identical), NEURL4 (22% identical), NEURL3 (18% identical).
Diseases named in the same sentence as NEURL1B in open-access papers:
NEURL1B is named in the same sentence as 6 diseases in open-access papers, as found by Europe PMC text mining. Sharing a sentence is not in itself a finding about the gene and the disease. The quoted sentences say what the papers report.
colon cancer (4 papers, 2020 to 2024). "For example, neuralized E3 ubiquitin protein ligase 1B (NEURL1B) is known to act as a tumor suppressor gene in colon cancer and medulloblastoma." (PMID 36291764, 2022). "A possible reason was speculated based on the precious analysis, we found that NEURL1B might be a tumor suppressor gene in colon cancer, whose decrease could further reduce this antagonism." (PMID 32742189, 2020). "Besides, protein expression analysis from THPA tool and clinical samples also showed NEURL1B was overexpressed in colon endothelial cells and glandular cells than colon tumor cells." (PMID 32742189, 2020).
lung adenocarcinoma (1 paper, 2022). A carcinoma that arises from the lung and is characterized by the presence of malignant glandular epithelial cells. "However, in our study, we found that NEURL1B acts more like an oncogene in lung adenocarcinoma cells." (PMID 36291764, 2022).
Right ventricular cardiomyopathy (1 paper, 2021). Right ventricular dysfunction (global or regional) with functional and morphological right ventricular abnormalities, with or without left ventricular disease. "Therefore, we speculated that NEURL1B might participate in TR by influencing the Notch-signaling pathway to cause right ventricular cardiomyopathy." (PMID 34603374, 2021).
tumor (5 papers, 2018 to 2024). "In addition, some clinicopathological variables, including age, tumor stage, lymph metastasis and clinical stage, were negatively associated with NEURL1B expression using χ2-test analysis." (PMID 32742189, 2020). "Thus, our findings suggested that NEURL1B participated in the pathological processes of CC as a tumor suppressor gene." (PMID 32742189, 2020). "Interestingly, NEURL1B was highly expressed in the HCC tissues, while its lower mRNA expression levels were associated with worse survival, which could be attributed to the decreased levels of immune cell infiltration in the tumor microenvironment." (PMID 38562021, 2024). "Importantly, there existing be an significant intersection between miRNAs-target pathways and NEURL1B-target pathways, suggesting that miR-17 and miR-27a might promote tumor cell malignant property by targeting NEURL1B degradation via the activation of PI3K/AKT signaling pathway." (PMID 32742189, 2020). "Besides, χ2-test analysis also revealed that NEURL1B expression was not related to multiple clinicopathological variables, including age, gender, tumor stage, lymph metastasis, distant metastasis and clinical stage." (PMID 32742189, 2020).
NEURL1B also shares sentences with these, for which no sentence is quoted: cancer (2 papers); medulloblastoma (1).